IL6 (interleukin 6)
Diseases named in the same sentence as IL6 in open-access papers (continued):
Sharing a sentence is not in itself a finding about the gene and the disease.
infection (continued). "In regards to common gene expression patterns on infection, Cameron and colleagues demonstrated expression of interleukin 6 (IL-6) signaling/complement genes and interferon response genes; however, reinfection resulted in decreased interferon response gene expression." (PMID 33468694, 2021). "Next, we investigated whether the multiplicity of infection influences IL-6 secretion and whether 3T6 fibroblast cells are able to recognize MPyV." (PMID 33923020, 2021). "When we assessed the cytokines production in the spleen and liver of the animals, we observed higher levels of IL-6 in neutropenic animals 1- and 2-days post infection together with an increased level of IL-10 in the liver of these animals 2-days post infection." (PMID 34642440, 2021). "IL-6 can be used as an inflammatory marker for severe infection." (PMID 33675295, 2021). "Again, there was a significant reduction in IL-6 secretion after both 12 and 24 h of infection." (PMID 34280250, 2021). "This inflammatory mediator has also previously been detected in CHIKV-induced persistent arthralgia, and we have recently shown that infection by MAYV of primary human chondrocytes leads to IL-6 production." (PMID 33799906, 2021). "In young (≈11 weeks old) SG+/+, SG+/− and SG−/− congenic littermate mice we assessed weight and intestinal morphological changes, and analyzed serum levels of IL-6 as well as the transcriptional expression levels of intestinal cytokines and chemokines on day 12 post infection." (PMID 34335577, 2021). "IL-6, IL-12, IL-8, interferon-gamma, and IL-1β all show increased secretion 48 hours after infection; however, the greatest (and most statistically significant) increase is shown by IL-6 equating to a fourfold increase above that of the uninfected control 48 hours postinfection." (PMID 34152044, 2021). "IL-6 modulates the immune response to mycobacteria and has various effects dependent on the nature of the challenge; mouse infection models have inconsistently shown that IL-6 signaling is protective, favors, or does not significantly affect M. tuberculosis or M. avium infection (48, –, 52)." (PMID 34607464, 2021). "However, their amounts rapidly change in response to pro-inflammatory cytokines released by innate immune cells during the course of an infection, with interleukin-6 (IL-6) and interleukin-1 (IL-1)-type cytokines as the leading inducers." (PMID 34858876, 2021). "could provoke the activation of T cells, monocytes/macrophages, and natural killer (NK) cells, which have important roles in the production of pro-inflammatory cytokines such as TNF-α, IL-6 and IL-1, particularly during the acute phase of infection." (PMID 34666703, 2021). "Although our previous study implicated TRIF, a downstream adaptor protein of endosomal TLRs, as being required for full IL-6 secretion following infection of human U937 cells by the clinical isolate L. pneumophila strain 130b, a more thorough examination was needed." (PMID 34280250, 2021). "Similarly, our study showed that NLRP6 mediates the secretion of IL-1β and IL-6 during macrophages infection with S. pneumoniae." (PMID 33918100, 2021). "In hemodialysis patients, serum iFGF23 is not correlated with hs-CRP or IL-6, but is an independent predictor of the risk of infection." (PMID 33416083, 2021). "C-reactive protein (CRP) is a sensitive but non-specific marker of systemic inflammation and is primarily produced by hepatocytes under transcriptional control by IL-6 in response to infection, trauma, surgery, burns, tissue infarction, advanced cancer, and chronic inflammatory conditions." (PMID 34361836, 2021). "Infection with CT can cause direct damage to sperm, reducing the sperm concentration, motility, and vitality, and can increase pH, lipid peroxidation (LPO), and even proinflammatory cytokines such as IL-1β and IL-6 in semen of infertile men." (PMID 34577786, 2021).
infection (continued). "In addition to the culture result, serum IL-6 level was also influenced by pathogen number, with polymicrobial infections displaying a higher IL-6 level than monomicrobial infections." (PMID 34595243, 2021). "Surprisingly, IL-6 was elevated in infections by clfA, sasC, and atl deletion mutants." (PMID 34484165, 2021). "Taken together, the data showed that CdtB up-regulated Il-6 protein expression during infection." (PMID 33777833, 2021). "Interestingly, when T. gondii-infected BeWo cells were treated with hemin for HO-1 induction, the levels of IL-6 were significantly upregulated, being higher than those released only in response to infection." (PMID 33912151, 2021). "Moreover, infection with NTHi resulted in higher production of IL1β, IL6, and TNFα in Cyld−/− mice compared to WT mice." (PMID 33808506, 2021). "Interestingly, GL pretreatment effectively decreased the upregulation of pro-inflammatory cytokines (IFN-γ, TNF-α, and IL-6) induced by ST infection in spleen and liver, and increased secretion of anti-inflammatory cytokine IL-10 in spleen." (PMID 34239908, 2021). "Surgeons often use a combination of inflammatory serum biomarkers such C-reactive protein (CRP) or interleukin-6 (IL-6), synovial markers, microbiological findings and clinical factors such as wound healing to assess the resolution of infection and to guide the timing of second stage reimplantation." (PMID 33795812, 2021). "Besides, TNF-α and IL-6 are pleiotropic cytokines produced mainly by neutrophils, which participate in cell trafficking, inflammatory responses, and host defense against infection." (PMID 33815381, 2021). "Comparison of the individual donors regarding IL-6 production revealed that this trend could be observed upon infection of M2 macrophages with RVFV, H1N1−1, and H3N2-1 for each donor tested." (PMID 34122407, 2021). "PFO is speculated to induce intravascular hemolysis and the production of proinflammatory cytokines, such as TNF-α, IL-5, IL-6, and IL-8 beginning in the early stage of infection in hosts infected with C. perfringens." (PMID 34385995, 2021). "Our analysis supports a model in which cytokine production by inflammatory macrophages at sites of infection may result in increased concentrations of systemic IL-6 and IL-10, promoting the expansion of myeloid cells expressing the MS1 gene program." (PMID 34103408, 2021). "IL-6 has demonstrated a protective role in the host response to infection." (PMID 33628091, 2021). "Furthermore, Aβ1-42 strengthened the binding of the S1 of SARS-CoV-2 to ACE2 and increased the viral entry and production of IL-6 in a SARS-CoV-2 pseudovirus infection model." (PMID 34360989, 2021). "As infection progressed in the vehicle controls, increased amounts of IL-6 and TNF-α, along with chemokines responsible for monocyte and neutrophil recruitment (CCL2, MIP-2a, and CCL4), were detected in the serum, and this pattern of inflammation was mirrored in the lungs." (PMID 34835277, 2021). "The results indicated that the expression of apoptosis-associated signal protein caspase-3 and the contents of inflammatory cytokines including tumor necrosis factor- (TNF-) α, interleukin- (IL-) 1β, and IL-6 were remarkably reduced by BPV treatment or LV-siPTEN infection." (PMID 33777313, 2021). "IL-6-/- mice exhibited higher severity and lethality upon infection than WT mice." (PMID 34777390, 2021). "However, in the 3D-skin model we observed a significant difference in the release of IL-6 after 24 h of infection." (PMID 35052714, 2021). "Environmental stress and infection trigger the expression of IL-6 for host defence." (PMID 33767260, 2021). "However, high levels of IL-6 at the resolution stage downregulate TGFβ and prevent resolution of infection/disease." (PMID 33571211, 2021). "However, the BMDC or BMDM from WT and PARP9 KO mice were comparable in terms of the proinflammatory cytokine IL-6 after infection by those RNA viruses." (PMID 33976210, 2021).
infection (continued). "B.1.351 infection in mice resulted in efficient virus replication with high titers in lungs and tracheas, severe pathological lung lesions, and inflammatory responses with elevated IL-6 and IL-10 expression." (PMID 34907154, 2021). "The mRNA expression of various inflammatory cytokines (Il-6, Tnf-α, Ifn-γ, and Ifn-β) and chemokines (Ccl2, Ccl4, Ccl12, Cxcl1, and Cxcl10), but not Il-1β, was elevated in the lungs at 2 dpi, in the early stage of infection." (PMID 34463644, 2021). "Pro-inflammatory cytokines, TNF-α and IL-6, are useful markers of infection severity." (PMID 34485172, 2021). "The question of blocking host inflammatory pathways in infection related lung pathology has been shown into sharp focus by the COVID-19 pandemic where treatment with dexamethasone or IL-6 inhibition can have a beneficial effect when used at the correct stage of the disease." (PMID 34539670, 2021). "Outside of its role during disease, infection or stress, IL-6 is present at low expression levels." (PMID 33925531, 2021). "IL-6 is a potent cytokine that controls a wide range of in vivo activities and is recognized for its role in shifting from nonspecific innate immunity to extremely specific, adaptive immunity against infection." (PMID 34832674, 2021). "Moreover, infection of brain perivascular cells by JEV, and an associated induction of proinflammatory cytokines (IL-6 and RANTES) was confirmed in vivo in mice." (PMID 34424156, 2021). "Interestingly, IL-1RA plays an important role in lipid metabolism, fever generation, neutrophil chemotaxis, positive regulation of IL-6 production, and the acute-phase response of infection." (PMID 34131192, 2021). "Thus, the immunosuppressive effect of IL-10 in synergy with IL-6, probably supports viral persistence or secondary infection, resulting in the more severe clinical outcome in influenza A(H1N1)pdm09 virus." (PMID 34946862, 2021). "Based on the central role of pro-inflammatory cytokines in the anti-Ct response, we hypothesized that Ct infection would increase the expression of pro-inflammatory cytokines such as IL-6, IL-8, and TNF-α." (PMID 34684219, 2021). "This was in conjunction with reduced levels of IL-6 upon in vitro infection." (PMID 33441583, 2021). "The upregulation of these chemokines might attract the immune cells to the site of infection and leads to increase in synthesis of IL-6." (PMID 33406695, 2021). "Infection of the lung cells using SARS-CoV-2 spike D614 and spike Delta (B.1.617.2) variant pseudotyped lentivirus particles was efficiently prevented by the extract and so was virus-triggered pro-inflammatory interleukin 6 secretion." (PMID 34681279, 2021). "We hypothesize that proinflammatory cytokines (TNF, IL-1, IL-6) play an essential role in promoting chemokine production during early infection because these inflammatory cytokines are usually decreased at the late phase." (PMID 34368012, 2021). "During this phase of infection, the activation of the immune system requires specific modifications to the energy metabolism mechanisms used by cells, wherein the macrophagic cytokine IL-6 plays a key role." (PMID 33550983, 2021). "We found that infection with M. mulieris significantly elevated multiple proinflammatory markers (IL-6, IL-8, TNF-α and MCP-1) and altered metabolites related to energy metabolism (nicotinamide and succinate) and oxidative stress (cysteinylglycine, cysteinylglycine disulfide and 2-hydroxygluatrate)." (PMID 35004344, 2021). "Uncontrolled IL-6 trans-signaling could also be explained by this mechanism, from which a picture of how infection worsens can be envisioned." (PMID 33628091, 2021). "Likewise, higher cytokine production of type I IFNs and IL-6 was observed in WT virus-infected mice at day 7 post-infection, suggesting a consequence of different viral titers of two viruses." (PMID 34610835, 2021).
infection (continued). "Of them, 45 patients with positive PCR Sars-Cov-2 laboratory-confirmed infection, presented all the required laboratory variables at baseline and further presented D-dimer, IL-6, and ferritin during the follow-up; thus, they were included in this retrospective analysis." (PMID 33596963, 2021). "IL-6 plays important roles in inflammation, infection responses, immunity and disease." (PMID 34209942, 2021). "While IL-6 is required during infection and injury to stimulate and activate host defenses through its pleiotropic effects on inflammation and immunomodulation, the aggressive secretion of IL-6 is known to contribute to chronic inflammation and associated pathologies." (PMID 33070170, 2021). "Terms that are related to inflammation included chronic inflammation, T cells, macrophages, immune response, infection, neutrophils, NF-kappa B, IL-6, B-cells, Cox-2, IFN-gamma, immunomodulation, IL-10, IL-8, lymphocytes, NF-kappa-B, neutrophil, cytokines, and chemokines." (PMID 34490346, 2021). "However, unstimulated HMECs secreted IL-6, and the levels were increased by 1.5 fold after OT infection." (PMID 34368012, 2021). "Additionally, T. denticola has been shown to degrade IL-1β and IL-6, and infection of both P. gingivalis and T. denticola synergistically stimulated the production of IL-6 by macrophage-like cells." (PMID 34079525, 2021). "Additionally, at 2 weeks PC, the level of either IL-1β or IL-6 was un-influenced by post-infection immunotherapy, when compared to controls." (PMID 34777338, 2021). "Over the 4 h of infection we detected increasing amounts of IL-8 and IL-6." (PMID 34015044, 2021). "IL6 and other proinflammatory cytokines/chemokines, steroids, and miRNAs upregulate the fibrinogen synthesis up to 10-fold during the acute phase of injury and infection." (PMID 34025688, 2021). "CRP production is stimulated by IL-6 and is produced by the liver as a response to infection." (PMID 34590796, 2021). "We did not observe any major differences in serum cytokine levels between WT and Dectin-2 KO mice following infection with these Candida spp., however, Dectin-2 KO mice displayed a subtle elevation in serum IL-6 levels 1-week post infection with C. albicans or C. tropicalis." (PMID 33717025, 2021). "These alterations were accompanied with the elevated transcriptional level of 10 innate immune genes with infection time, where il-1b, il-6, il-8, and il-10 exhibited a higher expression at 33°C than at 18°C and was attenuated by exogenous myo-inositol in both groups." (PMID 34566956, 2021). "IL-6 levels were higher than the range of detection in burned mice with infection by 12 hpb." (PMID 34152806, 2021). "The IL-8 cytokine secretion in epithelial cells seems to peak later than IL-6 and 10 during infection and is maintained even in advanced stages; moreover, the chemokine seems to be secreted in a distinct fashion depending on the side of the affected epithelium." (PMID 34578465, 2021). "It is being postulated whether morbidity from IFI may, in part, be a consequence of an unnecessarily prolonged or exaggerated proinflammatory immune response including interleukin 6 (IL-6) post-infection, in a host with dysregulated or compromised immunity." (PMID 34436195, 2021). "To test how IFNγ may modulate the inflammatory IL-8 and IL-6 responses from the epithelial cells, we added IFNγ into the medium of the biomimetic flow-chamber one hour before infection and measured the inflammatory response." (PMID 34015044, 2021). "IL-6 is a pro-inflammatory cytokine, expressed during states of inflammation and infection." (PMID 34944378, 2021). "Together, these data emphasize a vital role for IL-6 in the host immune response to infection." (PMID 33628091, 2021). "Additionally, compared with infection for 5 h, infection with purified CsgA protein for 3 h significantly decreased IL-6 levels to 1148.51 pg/mL (HTB-5 cells) and 1169.74 pg/mL (HMC-1 cells)." (PMID 34835359, 2021).
infection (continued). "Upon infection, the immune system triggers the release of immune mediators including pro-inflammatory cytokines such as tumor necrosis factor-alpha (Tnfa), interleukin-1 (Il-1), interleukin-6 (Il-6), and the type I interferons (Ifn-a/b)." (PMID 34768822, 2021). "We found that many cytokines messenger RNAs (mRNAs), including Il1b, Il5, Il6, Il10, Il12a/Il12p70, Ifng, Ccl4, Ccl5, Tnfa, Gcsf, Cxcl1, Il1a, and Il3, were significantly induced upon B.1.351 infection in the lungs of hACE2 transgenic, BALB/c, and C57BL/6 mice." (PMID 34907154, 2021). "Using mRNA hybridization, we further show that uninfected bystander cells actively contribute to the resolution of infection by producing IL-6 and TNF-α, which, via paracrine signaling, activate IRF1/IRG1 and strengthen the antimicrobial activity of infected macrophages." (PMID 34607464, 2021). "In addition, honey induces monocytes (MM6 cells) to secrete cytokines, tumor necrosis factor-α (TNF-α), interleukin-1 (IL-1), and interleukin-6 (IL-6), which activate the immune response to infection." (PMID 34443372, 2021). "Notably, the proinflammatory factor IL-6 and anti-inflammatory factor IL-10 were both increased during infection." (PMID 34593766, 2021). "In addition, Il6, Il10, and Tnfα mRNA levels were also increased at 4 h post-infection, then reduced at 24 h post-systemic S. aureus infection." (PMID 34040603, 2021). "Inflammatory cells infiltrate the sites of infection at an early stage of the infection with SARS-CoV2 and cause a stormy release of pro-inflammatory cytokines like IL-6, IL-17A, TNFα, IFNγ, IL-1α/β, and chemokines like CC-chemokine ligand 2 (CCL2) as well as CXC-chemokine ligand 10 (CXCL10)." (PMID 33643316, 2021). "During blood-stage infection, in response to the presence of the parasite, the host's immune system produces proinflammatory cytokines including IL-6, IL-8, IFN-γ, and TNF, cytokines which play a pivotal role in controlling the growth of the parasite and its elimination." (PMID 34790829, 2021). "In the same study, the infection of murine cDCs with the HSV-1 TLR2* variants indicated that both, TLR2 and TLR9 sensors are activated with these variants and are associated with the secretion of proinflammatory cytokines IL-6 and IL-12." (PMID 34895058, 2021). "We selected IL-6, IL-8, and TNFα as their production was markedly enhanced post-infection." (PMID 34367171, 2021). "Whether IL-6 released by B cells participates in the regulation of neutrophil recruitment into the MZ during the early phase of bloodborne pathogen infection remains to be determined." (PMID 34040603, 2021). "This seems to indicate that the increase in IL-6, IL-8 and IL-10 is a common result of infection." (PMID 34925324, 2021). "Collectively, these results suggest that SARS-CoV-2 can trigger macrophages and DCs to secrete IL-6 and IL-1β, which might directly decimate lymphocytes following infection in vivo." (PMID 33995382, 2021). "In conclusion, our data support that the transcriptional pathways analyzed by RNAseq are representative of both syncytia and non-fused trophoblasts and that PHT expressed pro-inflammatory cytokines independently of their fusion and infection status (at least for IL-6, IL-8, and TNFα)." (PMID 34367171, 2021). "There is growing evidence that CRP plays important roles in inflammatory processes and host responses to infection including the complement pathway, apoptosis, phagocytosis, nitric oxide (NO) release, and the production of cytokines, particularly interleukin-6 and tumor necrosis factor-α." (PMID 33534859, 2021). "The comparison of IL-6 levels in the serum and ECCs of HR-HPV-positive patients revealed higher levels of IL-6 in the ECCs, suggesting that IL-6 is mainly produced at the site of infection and that the immune response in the same patient changes at the systemic level." (PMID 33750983, 2021). "IL-6-/- mice exhibited high severity and lethality upon infection than WT mice." (PMID 34777390, 2021).